BCL2 (BCL2 apoptosis regulator)
Diseases named in the same sentence as BCL2 in open-access papers (continued):
Sharing a sentence is not in itself a finding about the gene and the disease.
follicular lymphoma (continued). "Bcl2, the first apoptotic regulator identified through its involvement in the t14;18 chromosome translocation that hallmarks follicular lymphoma, acts by promoting cell survival and osteopontin stimulates expression of anti apoptotic proteins." (PMID 19759912, 2009). "Patients with follicular lymphoma whose bone marrow harvests are cleared of bcl-2-positive cells have increased relapse-free survival compared with patients whose bone marrow harvests remain positive." (PMID 14562003, 2003). "Bcl-2, the gene over-expressed in follicular lymphomas (FL), is able to block chemotherapy-induced apoptosis." (PMID 10555759, 1999). "We evaluated the prognostic role of peripheral blood polymerase chain reaction (PCR) assay for detection of the bcl-2(MBR)/J(H) rearrangement in 59 patients with follicular lymphoma (FL) treated at our centre since 1989." (PMID 9218729, 1997). "Therefore, IHC staining for BCL-2 is often used in the diagnosis of follicular lymphoma as BCL-2 positivity in germinal center B-cells is present in most cases." (PMID 41552389, 2026). "Furthermore, in three cases of TdT‐positive HGBCL‐MYC/BCL2, studies of previous or concurrent follicular lymphoma demonstrated their divergent evolution from an IGH::BCL2‐positive cell population following acquisition of MYC translocation." (PMID 41047873, 2025). "Strong expression of bcl‐2 and CD10 may suggest secondary cutaneous involvement by follicular lymphoma, and bcl‐2 expression in > 75% of cells may be associated with an increased risk of skin recurrence in PCFCL." (PMID 40495407, 2025). "Furthermore, many BCL cases with MYC and BCL2 rearrangements are derived from transformed follicular lymphoma (FL), where the MYC rearrangement typically occurs during transformation." (PMID 41142614, 2025). "However, such a correlation has been made in follicular lymphoma in which the BCL2 gene is characteristically translocated to the IGH locus." (PMID 39664277, 2024). "It was found that BCL-2 expression, especially in the case of BCL-2 translocation to immunoglobulin heavy chain locus, might be the causative of “follicular lymphoma”." (PMID 39463509, 2024). "Bcl2-Tg mice developed lymphadenopathy and splenomegaly and died around 60 weeks (median survival of 64 weeks), which is significantly shorter than wild-type mice suggesting follicular lymphoma development as reported." (PMID 37304286, 2023). "Here, using both human cell lines and patient samples we identify an increase in insertion and deletion events (indels) at two ABCs, the CRLF2 ABC linked to LAs with Ph-like ALL and the non-LA linked BCL2 ABC linked to follicular lymphoma." (PMID 37790327, 2023). "In addition, each contingent showed its own pathogenic variants, such as BCL2, KMT2D, EP300 in the follicular lymphoma contingent, and XPO1, TNFAIP3, and CREBBP in the cHL contingent." (PMID 36428786, 2022). "In this case, both follicular lymphoma and plasma cells were positive for BCL2 by immunostaining." (PMID 36225194, 2022). "Moreover, Bcl2 promoter change from P1 to P2 occurred, similarly to native follicular lymphoma cases." (PMID 34210001, 2021). "High levels of BCL-2 and/or BCL-2 “dependence” are observed in patients with follicular lymphoma, mantle cell lymphoma, diffuse large B-cell lymphoma, and adult leukemias, and BCL-2 inhibition in patients with these diagnoses has led to promising treatment results." (PMID 35008312, 2021). "In addition to follicular lymphoma (FL), overexpression of BCL2 through several distinct molecular mechanisms was found in most B-cell lymphoproliferative disorders and myeloid malignancies." (PMID 34576319, 2021). "Additionally, specific chromosomal translocations common in follicular lymphomas juxtapose BCL2 with the IGH immunoglobulin locus, causing overexpression of the anti-apoptotic BCL2 and contributing to tumourigenesis." (PMID 34573358, 2021).
follicular lymphoma (continued). "B-cell lymphoma 2 (Bcl-2) is a proto-oncogene that was first identified in follicular lymphoma." (PMID 32570722, 2020). "A large proportion of follicular lymphomas with Bcl-2 overexpression are transformed into DLBCL." (PMID 31892356, 2019). "While disappointing, this may not be surprising given the potential intratumoral heterogeneity of BCL-2 expression in follicular lymphomas." (PMID 30406027, 2018). "Although multiple studies on MYC/BCL2 DHL have been published, to date no study has systemically compared the clinicopathologic features and prognostic factors between patients with de novo MYC/BCL2 DHL versus those patients with a history of follicular lymphoma (FL)." (PMID 27203548, 2016). "Nevertheless, it is tempting to speculate that in follicular lymphoma patients (which typically display BCL2 overexpression) with strong kidney infiltration ETV6/RUNX1 target genes could be involved." (PMID 26919255, 2016). "Importantly, the ETV6/RUNX1 fusion product and the antiapoptotic protein BCL2 cooperate in the development and progression of follicular lymphoma." (PMID 26919255, 2016). "It is the second member of a range of proteins initially described in chromosomal translocations involving chromosomes 14 and 18 in follicular lymphomas, placing BCL-2 under the control of the immunoglobulin heavy-chain promoter resulting in its deregulated high level of expression." (PMID 27462919, 2016). "The most important apoptosis-related gene in CLL is BCL2 (B-cell leukemia/lymphoma).We first described in follicular lymphoma as translocated to Ig heavy chain gene locus, for many years, and BCL2 has been considered as one of certain contributors to CLL development." (PMID 24337970, 2015). "The bcl-2 gene was first described as an oncogene in follicular lymphoma." (PMID 24555747, 2014). "The sequestration of Bim may explain the marked chemosensitivity of CLL and follicular lymphoma (FL) that express abundant Bcl-2." (PMID 23431463, 2013). "In addition, we used bcl-2 immunostaining, with alternative monoclonal antibodies (124 and 100/D5 clones), to help in the diagnosis of follicular lymphoma and to reduce false negatives, since reactive follicular center cells are negative for bcl-2." (PMID 22257663, 2012). "Lymphoid hyperplasia may be differentiated from follicular lymphoma presenting as lymphomatous polyposis by Bcl-2 immunostaining of follicular germinal centres." (PMID 21481240, 2011). "The bcl-2 gene was firstly described as an oncogene in follicular lymphoma." (PMID 22216342, 2011). "Indeed, genetic alteration of the bcl-2 gene located on chromosome 18 is considered to be a key process in the pathogenesis and chemoresistance of human tumors, such as follicular lymphoma." (PMID 17430582, 2007). "This conclusion stemmed primarily from the effects of deregulated bcl-2 expression in follicular lymphoma, which resulted in aberrantly prolonged B-cell survival, increased accumulation of transforming mutations, and accelerated transition to more aggressive and therapy-resistant disease." (PMID 14676801, 2003). "However, BCL2 rearrangement is certainly common in systemic follicular lymphoma and rare in PCFCL." (PMID 37047176, 2023). "Although the main diagnostic clues of follicular lymphoma bcl2 expression and BCL2 rearrangement–are often lacking in PCFCL, they may be seen in PCFCL." (PMID 37047176, 2023). "Constitutive over-expression of BCL2 in all hematopoietic lineages, in transgenic mice where the human BCL2 gene is fused to the Vav gene promoter, has a potent effect on the survival, development and maturation of many blood cell types and results in increased incidence of follicular lymphoma." (PMID 33914737, 2021).
follicular lymphoma (continued). "Synergy was most prominent in DLBCL and follicular lymphoma lines and was seen with both approved and emerging drugs used to treat B-cell malignancies, including dexamethasone, inhibitors of the B-cell receptor signaling pathway, such as ibrutinib, and the BCL-2 inhibitor venetoclax." (PMID 30067771, 2018). "For example, follicular lymphoma (FL) is common in adults but rare in children and exceptionally rare, if limited to those with IGH::BCL2." (PMID 39707053, 2025). "We reported a 66-year-old female was firstly diagnosed with follicular lymphoma, but presented with disease progression to DLBCL/HGBL-MYC/BCL2 during the treatment with BR regimen." (PMID 40230856, 2025). "Immunohistochemistry for general lymphoma markers (CD19 and CD20) and follicular lymphoma-specific markers (CD10 and Bcl2) was positive, while Congo Red staining was negative." (PMID 40342409, 2025). "Histopathological findings in this case align with the features of follicular lymphoma, characterized by nodular architecture and the expression of B-cell markers such as CD20 and BCL2." (PMID 40979429, 2025). "Approximately 5% of low-grade follicular lymphomas (LGFL) show a diffuse pattern and ~10% lack the BCL2 rearrangement." (PMID 40861583, 2025). "Group II is similar to the minority BCL2− follicular lymphoma of extranodal sites or lymph nodes and lacks IGH-BCL2." (PMID 40034922, 2024). "The first official BCL-2 inhibitor was ABT-737, which has a high affinity for BCL-2, BCL-xl, and BCL-w and results in significant follicular lymphoma (FL) and CLL cell death in vitro." (PMID 39060763, 2024). "In follicular lymphoma, transformation usually results in DLBCL or high-grade B-cell lymphoma with MYC and BCL2 rearrangements." (PMID 36845702, 2023). "Among them, HGBL-DH was the most common, with 3 cases of MYC/Bcl-2 HGBL-DH (8.6%, including 2 cases complicated with follicular lymphoma) and 21 cases of MYC/Bcl-6 HGBL-DH (60.0%, including 1 case complicated with the hemophagocytic syndrome)." (PMID 35686130, 2022). "The dysregulation of these oncogenes drives B-cell hematological malignancies such as follicular lymphoma (BCL2 translocation, MLL2 inactivation) DLBCL (e.g. BCL6, BCL2 and MYC translocation) or Burkitt’s lymphoma (MYC translocation)." (PMID 33912162, 2021). "In a conclusion, the FL‐SJC cell line has been identified as a novel MYC/BCL2 double‐hit follicular lymphoma that can be used as a potentially available tool for the clinical and basic research, together with the drug development for MYC/BCL2 DHFL." (PMID 32459397, 2020). "In this report, we established a novel ‘double‐hit’ follicular lymphoma cell line, FL‐SJC, which we wish as a useful tool for the improved understanding of MYC/BCL2 ‘double‐hit’ FL." (PMID 32459397, 2020). "BIRD-2 disrupts endogenous Bcl-2/IP3R complexes, thereby triggering Ca2+-driven apoptosis in different malignancies, including CLL, DLBCL, multiple myeloma, follicular lymphoma, and small cell lung cell carcinoma." (PMID 29899382, 2019). "Biopsy of the cervical node showed expanded lymphoid follicles with atypical germinal centers that were positive for CD10, BCL-2, and BCL-6, consistent with follicular lymphoma (FL)." (PMID 30271641, 2018). "These similarities strongly support the origin of the large B-cell lymphoma from a follicular lymphoma in that CD10 and Bcl2 displayed a diffuse positive reaction." (PMID 25977881, 2015). "The patient's presentation initially resembled infectious mononucleosis due to a false-positive monospot test; however, subsequent workup revealed follicular lymphoma lacking the canonical BCL2/IGH translocation." (PMID 42057973, 2026). "The index case is PTFL, initially identified in children and later in adults, with absent IGH::BCL2 and better prognosis compared to follicular lymphoma." (PMID 39707053, 2025). "One patient (Patient 5) had a concomitant diagnosis of follicular lymphoma grade 1–2, BCL2 + that did not require specific treatment." (PMID 40913745, 2025).
follicular lymphoma (continued). "The pathology was follicular lymphoma grade 1: centrocyte or centroblast-like lymphoid cells in ill-defined geminal center-like structures were positive for CD20, negative for CD3, positive for CD10, BCL2, and BCL6." (PMID 40896064, 2025). "However, TdT is also expressed in rare cases of diffuse large B‐cell lymphoma (DLBCL) transformed from follicular lymphoma (FL) with dual MYC and BCL2 rearrangements." (PMID 41047873, 2025). "This case adds to the heterogeneity of BCL2-negative follicular lymphomas and the understanding of the biology and management of these complex cases." (PMID 40861583, 2025). "The BCL2 protein produced in follicular lymphomas with or without BCL2 gene rearrangements is identical to the BCL2 protein found in normal cells." (PMID 40204952, 2025). "In contrast, paediatric-type follicular lymphoma shows recurrent somatic mutations in the MAPK pathway and the IRF8 gene and absence of BCL2, BCL6, MYC and IRF4 rearrangements." (PMID 38835967, 2024). "However, single-agent therapy with the BCL2-specific inhibitor venetoclax (ABT-199, PubChem 254741640) had only a 12% complete response (CR) rate in relapsed/refractory DLBCL and 14% CR in follicular lymphoma in a phase I study." (PMID 38893249, 2024). "Examples are low-grade lymphoma, including Bcl2-negative follicular lymphomas, B- or T-cell proliferations at specific sites, such as the skin, or in the context of immunodeficiency." (PMID 36845702, 2023). "BCL-2 was first identified through mapping of the t[12:18] chromosomal translocation, which results in a constitutive BCL-2 expression from the immunoglobulin locus and often underpins follicular lymphoma." (PMID 35349392, 2022). "Several events have been reported to be responsible for the upregulation of pro-survival Bcl-2 proteins; among the events is Bcl-2 translocation (first reported in follicular lymphoma), which is not prevalent among other cancers." (PMID 34830349, 2021). "The absence of Bcl‐2 positive B cells in the germinal center and lack of clonality of the B cells rules out a diagnosis of follicular lymphoma." (PMID 34258825, 2021). "Bcl-2 was initially identified due to its translocation in follicular lymphoma and was subsequently found to inhibit apoptosis rather than increase proliferation." (PMID 31273232, 2019). "Bcl-2 is known to be highly expressed in follicular lymphomas but the TCGA dataset has no informative information for this tumor." (PMID 31143550, 2019). "In our consultation practice, it was noted that many cases that were considered to represent follicular lymphoma (FL) without a BCL2 translocation were ultimately classified as nodal marginal zone lymphoma (NMZL)." (PMID 26949422, 2016). "In our case, although we considered the possibility of metastatic BC when analyzing the mesenteric biopsy, the immunohistochemical profile clearly revealed a nodular, low-grade (grade I) follicular lymphoma (CD20+, CD10+, BCL2+, CD23+, CD3−, CD5− and cyclin D1−)." (PMID 23419985, 2013). "Although not detected in our patient, BCL2/IgH gene rearrangements as seen in follicular lymphoma have been reported in some PPBL patients by using PCR technique." (PMID 22901769, 2012). "While the breakpoint on chromosome 18 is in the same region as that seen in follicular lymphoma, the gene involved is MALT1 rather than BCL2; rare cases of MALT lymphoma have reportedly been associated with the IgH-BCL2 fusion." (PMID 21318155, 2011). "Unlike follicular lymphoma that is positive for BCL-2, however, follicular hyperplasia is negative for BCL-2." (PMID 20584306, 2010). "Our data confirmed that bcl-2(MBR)/J(H) rearrangement detection by PCR at diagnosis is not a prognostic factor in follicular lymphoma." (PMID 9218729, 1997). "While BCL-2-negative follicular lymphoma has been reported in cats, reports in dogs remain limited." (PMID 40559769, 2025).
follicular lymphoma (continued). "Excisional biopsy of the right orbital mass showed follicular lymphoma grade 1: centrocyte or centroblast-like lymphoid cells in ill-defined geminal center-like structures were positive for CD20, negative for CD3, weakly positive for CD10, predominantly positive for BCL2 and BCL6." (PMID 40896064, 2025). "MYC/BCL2 double hit lymphoma (DHL) has been the subject of many studies; however, no study has systemically compared the clinicopathologic features and prognostic factors between patients with de novo disease versus those with a history of follicular lymphoma (FL)." (PMID 27203548, 2016). "CJ cells are not only DHL cells but also currently the only known centrocytic cell line, with a unique pathophysiology, suggesting that MYC/BCL2 DHL is heterogeneous and may provide insights into pathophysiologic mechanisms such as large cell transformation of follicular lymphoma." (PMID 26515759, 2015). "Cervical lymph node biopsy demonstrated follicular lymphoma with uniform BCL2 expression but no detectable BCL2/IGH fusion by Fluorescence in Situ Hybridization (FISH), confirming nontranslocation follicular lymphoma." (PMID 42057973, 2026). "BCL2-IGH rearrangement [t(14:18)], characteristic of nodal follicular lymphoma (FL) is typically absent in PCFCL, even in cases that show BCL2 expression." (PMID 40227781, 2025). "The neoplastic lymphocytes of follicular lymphoma characteristically express B-line markers (CD19, CD20, CD79a) and, in most cases, CD10, BCL6, LMO2, and BCL2; they are normally negative for CD5, CD23, and cyclin D1." (PMID 38534887, 2024). "IHC helps to distinguish this neoplasm since follicular lymphoma is positive for CD10 and bcl-2 and negative for CD5, CD23, CD43, and cyclin D1." (PMID 37958219, 2023). "Like follicular lymphoma, MCL is positive for CD20 and Bcl-2, but in contrast to follicular lymphoma, MCL is negative for CD10, BCL-6, as well as CD23." (PMID 27119356, 2016). "Notably, the B cells in the atypical nodules were negative for BCL2 and cyclin D1, crucial in distinguishing PTFL from adult-type follicular lymphoma." (PMID 39840177, 2024).